FASN (fatty acid synthase)
Diseases named in the same sentence as FASN in open-access papers (continued):
Sharing a sentence is not in itself a finding about the gene and the disease.
cancer (continued). "Therefore, it is likely that cancers other than KMLC rely on FASN and the Lands cycle to overcome ferroptosis." (PMID 35882862, 2022). "FASN has previously been reported as an oncogene in many cancer types." (PMID 35127296, 2022). "Previous experimental evidence has suggested that fatty acid synthase (FASN) may be involved in cancer metastasis, and have been investigated as a therapeutic target." (PMID 35392503, 2022). "In some hypoxic cancer cells, there is abnormal synthesis of fatty acids independent of extracellular availability thanks to the overexpression of FASN, a product of increased expression and activation of the sterol-regulating element-binding protein 1 (SREBP-1) due to HIF-1." (PMID 35745875, 2022). "The gene encoding FASN is frequently amplified in cancer; however, FASN inhibitors have failed to gain clinical approval." (PMID 35732120, 2022). "It is reported that FASN inhibitors increase the accumulation of LC3-II in a couple of cancers." (PMID 40396015, 2022). "Our results indicated that FASN plays an essential role in developing sorafenib resistance in HCC by regulating cancer metabolism; thereby, FASN inhibition may be a possible means to improve the efficacy of sorafenib in HCC treatment." (PMID 35742944, 2022). "We now uncover a novel FASN-driven facet of the so-called “mitochondrial priming” that mechanistically links the redox-buffering mechanism of FASN activity to the intrinsic apoptotic threshold in cancer cells." (PMID 34675185, 2021). "Thus, the results from our experiments and prior reports showing that tumor cells exhibit preferential utilization for extracellular lipids suggest that extralipogenic function should be the primary metabolic dysfunction of FASN in cancer." (PMID 34765544, 2021). "However, although FASN has been a therapeutic target for cancer for a few decades, FASN blockade has yet to be successful in clinical settings." (PMID 34948233, 2021). "Luteolin (3,4,5,7-tetrahydroxyflavone), a potent FASN inhibitor found in vegetables, fruits and medicinal herbs, was thought to exert its anti-cancer activity in CRC by the modulation of various tumor signal pathways, including the IGF-1, Keap1-Nrf2-ARE and Wnt-β-catenin pathways." (PMID 34200820, 2021). "FASN activity might regulate cancer cell survival by fine-tuning the mitochondrial threshold for apoptosis, known as “mitochondrial priming”." (PMID 34675185, 2021). "Evidence supporting the anti-cancer efficiency of FASN inhibitors in CRC is still accumulating." (PMID 34200820, 2021). "In many types of cancers, FASN is overexpressed and increased as the cancer develops." (PMID 34822423, 2021). "In addition, oleuropein can alter the function of key molecules involved in the onset and development of cancer such as MAPKs, c-Met proto-oncogene, and the fatty acid synthase (FASN) enzyme." (PMID 34836091, 2021). "If USP14 negatively affects FASN levels in cancer cells, it could be predicted that inhibition of both USP14 and FASN using siRNAs or inhibitors would restore reduced cancer cell viability by inhibiting only FASN." (PMID 34948233, 2021). "In particular, FASN, a key lipogenic enzyme that converts Acetyl-CoA and malonyl-CoA to palmitate, is drastically upregulated in many cancers such as breast, colon, lung, bladder, gastric, endometrial, ovary, kidney, pancreatic, head and neck, prostate, brain and melanoma." (PMID 34249759, 2021). "Previous studies have proved an evidence on the interaction between FASN and the process of epithelial-mesenchymal transition (EMT) in GC, which reveals that FASN may be a promising therapeutic target for the anti-cancer therapy." (PMID 34456997, 2021). "To overcome the limitations of FASN inhibitors as anticancer drugs, we speculated that simultaneously inhibiting the level and the activity of FASN could more potently suppress cancer cell growth." (PMID 34948233, 2021).
cancer (continued). "Indeed, many of the enzymes responsible for lipid synthesis, such as ATP-citrate lyase (ACYL), acetyl-CoA carboxylase (ACC) and fatty acid synthase (FASN) are highly up-regulated in cancer." (PMID 34249759, 2021). "However, little is known about the molecular determinants of cancer cell sensitivity to FASN inhibitors (FASNis), which is a major roadblock to their therapeutic application." (PMID 34675185, 2021). "Moreover, quantitative real-time PCR suggested that the expression levels of MAOB and LRP1 were downregulated in cancer tissues compared with paracarcinoma tissues, and the expression of FASN was upregulated." (PMID 34819038, 2021). "Importantly, MYC has been implicated as a mediator of both RAS and BCR-ABL-driven cancers and is shown to directly influence gene expression of ACACA, FASN, and SCD." (PMID 34399819, 2021). "Enzymes in de novo FAS pathway, including ACLY, ACC and FASN, are upregulated in numerous cancers." (PMID 34823530, 2021). "The expression of FASN was found to be inversely associated with drug resistance in BRAF-mutant cell lines, both in a set of six resistant/sensitive matched lines and in the Cancer Cell Line Encyclopedia." (PMID 34068792, 2021). "It was reported that FASN inhibitors increased the accumulation of LC3 II in a couple of cancers." (PMID 34620841, 2021). "Considering the identified side effects of chemical FASN inhibitors, scientists prefer to use the low cost and abundant natural herbal compounds instead, which may block the FASN activity in order to conquer cancer." (PMID 33939282, 2021). "Thus, the miR-497-5p/FASN axis operated as the downstream effector pathway through which SNHG25 played cancer-promoting roles in EC." (PMID 34789312, 2021). "Taken together, these results indicated that FASN binds to USP14 but may not be a direct substrate of USP14, and the expression level of USP14 is more important in modulating FASN levels than the activity of USP14 in cancer cells." (PMID 34948233, 2021). "We investigated the correlation between FASN DNA methylation and tumorigenesis in various cancers." (PMID 34879004, 2021). "Moreover, increased levels of FASN in cancer cells has been correlated to poor prognosis, and inhibition of FASN results in apoptosis of cancer cells." (PMID 34285285, 2021). "FASN, a crucial enzyme in de novo fatty acid synthesis, has been found overexpressed in cancers." (PMID 34421595, 2021). "Cancer cells frequently express high levels of FASN compared to their healthy counterparts." (PMID 33742137, 2021). "Based on the previous reports that Akt activation could be modulated by FASN in cancer cells, we were curious whether FASN was as well responsible for the phosphorylation of Akt in macrophages." (PMID 34642298, 2021). "Also, it is reported that FASN which is highly expressed in primary CRC and liver metastases are capable of upregulating expression of a transmembrane glycoprotein implicated in cancer metastasis called CD44, thus exerts a critical effect on CRC metastasis." (PMID 35003369, 2021). "Previous study showed SR9009 could induce the apoptosis of cancer cells by suppressing autophagy and de novo lipogenesis through repressing fatty acid synthase (FAS) and stearoyl‐CoA desaturase 1 (SCD1)." (PMID 34587364, 2021). "Tumor tissues may have aberrant activation of de novo lipogenesis due to an overexpression of fatty acid synthase (FASN), ATP citrate lyase (ACLY), and acetyl-CoA carboxylase (ACC), which is associated with unfavorable cancer outcomes." (PMID 34476174, 2021). "Inhibitors of fatty acid(FA) synthase(FASN) – the rate-limiting enzyme of endogenous FA synthesis that is overexpressed in OC – induce growth-arrest and apoptosis, rendering them promising candidates for cancer drug development." (PMID 33928023, 2021).
cancer (continued). "Although all of these genes have been linked to metabolic functions, most attention related to the growth and invasion of cancer cells has been directed to FASN, which is often overexpressed in tumor tissues and represents the lipogenic phenotype in cancer pathogenesis." (PMID 33226729, 2021). "FASN is highly expressed in cancer tissues compared with normal fallopian tubes." (PMID 34250022, 2021). "Thus, many cancers exhibit overexpressed fatty acid synthase (FASN), a key biosynthetic enzyme involved in lipogenesis." (PMID 34771610, 2021). "Taken together, our results and data indicate that FASN may become a new target for preventing the metastasis of tumor, thus providing a novel reference for the treatment against cancer." (PMID 34456997, 2021). "Furthermore, blocking the enzymatic activity of FASN can decrease phospholipid production, inhibit cell proliferation, and alter the metabolite profile in cancer cell lines." (PMID 35096815, 2021). "Furthermore, OA treatment decreased fatty acid synthase (FASN) protein levels, a critical enzyme in the lipogenic pathway that is frequently found to be overexpressed in cancer cells." (PMID 33671107, 2021). "Furthermore, we observed a decrease in the methylation level of FASN in cancer tissue compared to normal tissue for the selected probes (cg03386722, P = 1.34e-06, cg23244421, P = 0.03)." (PMID 34879004, 2021). "The genetic alteration level of FASN has been observed in various cancers." (PMID 34879004, 2021). "To determine whether USP14 plays a role as a regulator of endogenous FASN levels in cancer cells in the same manner as MPHs, we transfected various cancer cell lines with siRNA targeting USP14." (PMID 34948233, 2021). "Several studies have revealed a functional connection between FASN and cancers." (PMID 34879004, 2021). "FASN is the enzyme whereby the condensation between acetyl-CoA and malonyl-CoA, at the final catalytic step of FA synthesis, produces palmitate, and has been indicated as an emerging target to cancer." (PMID 34359950, 2021). "Regulation of FASN in cancers is partly owing to the transcriptional activation by SREBPs." (PMID 32714863, 2020). "However, FASN expression has been found to increase in various human cancers to promote cell proliferation." (PMID 32944403, 2020). "Plenty of previous studies on cancer cells showed that inhibiting FASN can increase apoptosis." (PMID 32676035, 2020). "Furthermore, the identification of FASN-positive tumor signatures can serve as predictive biomarkers to select cancer patients who will likely to benefit from FASN-targeted therapy." (PMID 32872164, 2020). "In addition to increasing the specificity of FASN inhibitors for clinical application, mechanisms by which cancer cells are resistant to these agents should also be investigated." (PMID 33083663, 2020). "As an inhibitor of fatty acid synthase, cerulenin could affect the proliferation and metastasis of cancer cells." (PMID 32486001, 2020). "Although several FASN inhibitors have been developed that display anti-cancer properties, it was important to determine whether more clinically applicable drugs share properties of C75 when directly compared using the same concentrations in the same models." (PMID 33083663, 2020). "Finally, we note that one trait associated with rapid tumor growth is an increase in FAS, and FASN has been explored as a cancer therapy target." (PMID 32735213, 2020). "FASN is also up‐regulated in cancer tissues and promotes invasion and metastasis of CRC." (PMID 33118286, 2020). "However, in cancer, the functional relationship between FASN and PPARα is controversial and it differs between cancer types." (PMID 32872164, 2020). "Several studies have suggested that FASN-mediated de novo synthesis of lipids may be a reasonable therapeutic target for the treatment of cancer and adiposity." (PMID 33569391, 2020).
cancer (continued). "In accordance with this, FASN inhibitors could be a very important therapy approach to induce a certain grade of cancer cell and cancer stem cell differentiation, in order to make tumors more sensitive and increase the efficacy of conventional therapy." (PMID 31936544, 2020). "FASN has received much attention as a cancer therapeutic target." (PMID 32695216, 2020). "It is estimated that ~90% FAs in cancer cells are synthesized by the enzyme FA synthase (FASN)." (PMID 32226926, 2020). "Although there are ongoing studies in our laboratory, this study did not provide evidence to demonstrate whether inhibition of both FASN and PD-L1 may have synergistic inhibitory effects on cancer progression." (PMID 32792852, 2020). "In terms of mechanism, we proved our viewpoint by inhibiting transcriptional activation of FASN through decreasing H3K4me3 modification at FASN gene promoter and thus suppresses FASN-mediated lipid acid metabolism and the proliferation and invasion of cancer cells." (PMID 32714863, 2020). "In addition, several sncRNAs have been reported to regulate the expression of FASN in many types of cancer." (PMID 33050166, 2020). "Next, we sought to assess whether the other FASN inhibitors share with C75 the ability to enhance the radiation-induced kill of cancer cells." (PMID 33083663, 2020). "This and the upregulation of fatty acid synthase (FAS) in many cancers have made researchers investigate whether inhibition of FAS could be used for cancer therapy." (PMID 32314087, 2020). "Overexpression of Akt increases the expression of ACLY, ACC, and FASN in human cancer cells." (PMID 32947972, 2020). "The influence of FASN on nucleus function is relatively unknown, although limited studies have shown that FASN is critical in mediating DNA damage response in cancer cells." (PMID 32872164, 2020). "Fatty acid synthase (FASN) is possibly the most studied enzyme related to FA metabolism and cancer." (PMID 33050166, 2020). "FASN is suggested to be a more vulnerable target in CSCs than in the bulk cancer cells." (PMID 32641978, 2020). "In addition, increased levels of FASN and related de novo lipogenesis have been observed in multiple cancer types, including tumors of the breast, gastrointestinal tract, prostate, bladder, ovary, lung, oral cavity, and head and neck." (PMID 33187130, 2020). "This is supported by in vivo studies employing EGFRvIII-bearing glioblastoma cells showing the high dependency of the cells on SREBP1 for survival and demonstrating that inhibition of SREBP1 and FASN, respectively, promotes massive tumor cell death in cancer cells bearing activated EGFR signaling." (PMID 33027921, 2020). "The significant increase in FASN expression in patients with suboptimal surgery has been correlated with the existing theory on a more aggressive cancer phenotype in the presence of FASN expression and excessive activity, which can affect EOC progression and recurrence." (PMID 33112541, 2020). "It is well known that some drugs have been used for metabolic diseases, such as FASN inhibitors, have been gradually developed for the field of anti-tumor therapy, and more overlap between metabolic diseases and cancer may be found in the future." (PMID 33364199, 2020). "FASN is a well-characterized driver of metabolic reprogramming in cancer cells." (PMID 33335078, 2020). "Not only FASN can be inhibited to target de novo lipid synthesis in cancer cells." (PMID 33415069, 2020). "Increased expression of fatty acid synthase (FASN), the terminal and crucial enzyme in de novo lipogenesis, has been linked to tumor metastasis, chemoresistance, and reduced patient survival in many cancers." (PMID 32046309, 2020). "In some cancers, a fusion of FASN and Estrogen receptor α (ER-a) genes has been described that may play a role in estrogen signaling." (PMID 32318352, 2020). "Treatment with a FASN inhibitor increases apoptosis and decreases cell growth in cancer cells." (PMID 30717356, 2019).
cancer (continued). "Two key steps in lipid synthesis that have been thoroughly described in carcinogenesis development are catalyzed by ATP citrate lyase (ACLY) and fatty acid synthase (FASN), where their inhibition could induce apoptosis and reduce tumour growth of cancer cells." (PMID 31040908, 2019). "Indeed, it has been shown, that blocking of FASN in cancer cells results in cell growth arrest and induction of apoptosis." (PMID 31159437, 2019). "Additional evidence linking FASN to cancer comes from experimental models." (PMID 31921669, 2019). "We investigated a potential cancer prevention role of FASN inhibitors." (PMID 31676791, 2019). "In addition to being lipid-lowering agents, fibric acid derivatives were also found to have anti-cancer effects through inhibition of FASN activity." (PMID 30824767, 2019). "Taken together, these features indicate that FASN is a potential target for cancer prevention." (PMID 31676791, 2019). "It interests us to investigate whether fenofibrate inhibits cancer cell growth through inhibition of FASN activity." (PMID 30824767, 2019). "Furthermore, drugs which act indirectly to activate AMPK, including metformin, aspirin and FASN inhibitors, have also been demonstrated to decrease proliferation of cancer cells and potentially sensitize cancer cells to radiation." (PMID 30774777, 2019). "In the fatty acid synthetase part, ACACA and FASN were upregulated in 4 cancer types." (PMID 31828117, 2019). "The overexpression of FASN forecasts a poor prognosis in cancer patients." (PMID 31242216, 2019). "Furthermore, investigations conducted in breast, pancreatic, and colorectal tumors showed that cancer patients exhibit elevated levels of FASN in the serum." (PMID 31921669, 2019). "Fenofibrate is known to have lipid-lowering effects, and it interests us to investigate whether fenofibrate inhibits cancer cell growth through inhibition of the FASN activity, similar to orlistat." (PMID 30824767, 2019). "Adequate FA supply is further supported by Akt- and HIF-1-dependent activation of SREBP-1, which in turn upregulates the expression of FASN (fatty acid synthase), an essential lipogenic enzyme, the activity of which is correlated with cancer progression and hypoxia induced chemoresistance." (PMID 30832409, 2019). "FASN is required for eliciting the anaplerotic shift of the Krebs cycle observed in cancer cells." (PMID 31676791, 2019). "Current evidence on the antineoplastic properties of main FASN inhibitors in cancer." (PMID 31921669, 2019). "Previous studies reported the overexpression of fatty acid synthase (FASN) in cancer." (PMID 31597357, 2019). "Moreover, orlistat, a FASN inhibitor slowed tumour growth and altered cancer metabolism as observed by the 11C-acetate/microPET imaging in xenograft mice." (PMID 31527721, 2019). "The important role of FASN for cancer biology has triggered the development of specific inhibitors." (PMID 31354474, 2019). "Recently, overactivated FASN has been found in different types of cancers." (PMID 31122252, 2019). "The significant roles of SCD and FASN in cancer development have been well established in the past." (PMID 31083642, 2019). "A role of FASN in EMT has been widely reported in previous studies of various types of cancer." (PMID 31027222, 2019). "However, proliferating cells, like several human cancers, have been shown to up-regulate FASN expression and take up free fatty acids to generate phospholipids." (PMID 29971237, 2018). "However, despite its importance in cancer progression several attempts to pharmacologically target FASN have failed until now, but a new FASN antagonist (TVB-2640) is now under evaluation in Phase I and II clinical trials." (PMID 30518103, 2018). "According to TarBase, both miR‐330‐5p and miR‐326 might directly interact with FASN, a metabolic oncogene in different types of cancer." (PMID 29722168, 2018). "Ongoing clinical trials indicate the efficacy for FASN inhibition in cancer." (PMID 29971237, 2018).